SIRT1 (sirtuin 1)
Diseases named in the same sentence as SIRT1 in open-access papers (continued):
Sharing a sentence is not in itself a finding about the gene and the disease.
Cognitive impairment (continued). "Interestingly, treatment with 50 mg/kg resveratrol daily upregulated the reduced SIRT1 expression and collectively improved the developmental synaptic plasticity and cognitive impairment in the male SD pups." (PMID 38416341, 2024). "Conversely, a lentivirus vector strategy to induce hippocampal overexpression of SIRT1 prevented AD‐cognitive impairment and exerted nootropic effects in animals with normal aging, which in cell cultures were shown to be done through neurotrophic and proteostatic mechanisms." (PMID 37701236, 2023). "Taken together, hippocampal Sirt1 knockdown could lead to hippocampal atrophy and its induced cognitive impairment in middle-aged mice, along with activation of tau hyperphosphorylation and synaptic damage." (PMID 35668361, 2022). "In this study, we demonstrated that RES could significantly prevent SEV-induced brain injury by reducing neuronal apoptosis and cognitive impairment, which was at least partly mediated by the SIRT1/RhoA signaling pathway in adult rats." (PMID 34247566, 2022). "In addition, in prior research by our lab showed that SIRT1 reduction in the cortex and hippocampus was accompanied by cognitive impairments in a mouse model of mild TBI." (PMID 35566074, 2022). "We found that LIG could reduce 5neuronal damage and improve cognitive impairment by regulating the SIRT1/IRE1α/XBP1s/CHOP pathway." (PMID 36017237, 2022). "In conclusion, these studies indicated that LIG could improve cognitive impairment by regulating the SIRT1/IRE1α/XBP1s/CHOP pathway in VaD rats." (PMID 36017237, 2022). "Some studies have shown that increasing the expression of SIRT1 could improve cognitive impairment in VaD rats by promoting angiogenesis, anti-inflammatory, antioxidant, and antiapoptosis." (PMID 36017237, 2022). "Finally, hippocampal tissues of the three groups were randomly isolated for western blotting to examine the potential mechanisms of Sirt1 knockdown in regulating hippocampal atrophy and cognitive impairment." (PMID 35668361, 2022). "In conclusion, Sirt1 gene has an obvious neuroprotective effect, and exploring its protective effect on cognitive function of healthy aged mice is of great significance for the prevention of cognitive disorders such as AD." (PMID 35668361, 2022). "Besides, it was found that LIG improved cognitive impairment by regulating the SIRT1/IRE1α/XBP1s/CHOP pathway in the hippocampus of VaD rats." (PMID 36017237, 2022). "Rats with a specific Sirt1 gene knockout or Sirt1 mutation without catalytic activity develop cognitive impairment, which is related to plasticity-related damage of the hippocampus." (PMID 36177213, 2022). "NAD+ ameliorated cognitive impairment and dampened neuroinflammation in CCH models in vivo and in vitro, and these beneficial effects were associated with mitochondrial protection and ROS inhibition via activating Sirt1/PGC-1α pathway." (PMID 34530866, 2021). "Also in AD animal models, activation or overexpression of SIRT1 was linked to neuroprotection and improved cognitive function, whereas cognitive deficits in SIRT1 knockout mice were aggravated." (PMID 33923297, 2021). "Triptolide administration improves cognitive impairments in VaD rats, increases SIRT1 expression, and decreases NF-κB expression; thus, its mechanism may be related to SIRT1/NF-κB signaling." (PMID 33532143, 2021). "Interestingly, our previous and other studies found that the expression of SIRT1 declined in hippocampal microglia with aging and contributed to age-related neuroinflammation and cognitive impairment in rodent." (PMID 33381265, 2020). "Our findings proposed a new mechanism of sevoflurane-induced neurotoxicity in the developing brain and suggested that these long-term cognitive deficits could be mitigated by activating SIRT1." (PMID 32148659, 2020).
Cognitive impairment (continued). "In addition, SIRT1 was downregulated in diverse models of cognitive impairment in vivo and in vitro, such as in juvenile C57BL/6J mice with dysmetabolism induced by high-caloric diet and neurotoxic primary hippocampal neurons caused by toxins." (PMID 29164153, 2017). "In addition, this protective effect of H2S against hippocampal damage and cognitive impairment was abolished by Sirtinol, an inhibitor of Sirt1." (PMID 29245987, 2017). "To investigate whether Sirt1 mediates the protective effect of H2S against CRS-induced hippocampal damage and cognitive impairment, we first explored the effect of H2S on the expression of Sirt1 protein in CRS-exposed rats." (PMID 29245987, 2017). "Moreover, reduced SIRT1 concentrations were associated with increased disease severity and poorer cognitive function, suggesting that SIRT1 may serve as a potential biomarker for both disease progression and cognitive impairment in Parkinson’s disease." (PMID 41601525, 2026). "In addition, SIRT1/FOXO1 signalling may be involved in cognitive impairment by regulating autophagy." (PMID 40008520, 2025). "Collectively, these studies suggests that SIRT1 is an essential regulator of hippocampal synaptic plasticity which are closely related to cognitive function and thus SIRT1 can be a potential therapeutic target against Pb induced cognitive impairment in early life." (PMID 38416341, 2024). "Therefore, we hypothesized that melatonin improved SCOP‐induced cognitive impairment through inhibiting SIRT1‐mediated ER stress." (PMID 39056330, 2024). "In this study, we explored whether SD during late pregnancy accelerates cognitive decline in aging offspring mice and, if so, whether long-term EE can ameliorate cognitive impairment through improving oxidative stress and neuroinflammation in a Sirt1/PGC-1α pathway-dependent manner." (PMID 38231482, 2024). "Besides, recent study found that SIRT1 is relevant to cognitive impairment in PD." (PMID 37718350, 2024). "However, how EE affects cognitive impairment in aging offspring resulting from gestational exposure to SD is unclear, as are the putative accompanying changes in mitochondrial function, oxidative stress, and the Sirt1/PGC-1α pathway." (PMID 38231482, 2024). "Klotho may antagonize oxidative stress, activate cellular autophagy, and inhibit neuroinflammation to reduce cognitive impairment by affecting the AMPK/SIRT1 signaling pathway, which plays an important role in glucose regulation, neuron proliferation, oxidative stress, and cognition.." (PMID 38505757, 2024). "However, we have already demonstrated that this cognitive impairment could be treated pharmacologically using this transgenic mouse model treated with the SIRT1 activating compound SRT1704." (PMID 37174668, 2023). "Thus, we hypothesized that diet control and/or physical exercise had a positive impact on the improvement in cognitive deficits related to the SIRT1-mediated pathways." (PMID 36999158, 2023). "Furthermore, our previous study has found that resveratrol could alleviate cognitive impairment by activating Sirt1 in aged rats after anesthesia and surgery." (PMID 36978961, 2023). "Thus, it is worth exploring whether CAPE also mediated the Sirt1 pathway to alleviate cognitive impairment in elderly mice after anesthesia and surgery." (PMID 36978961, 2023). "In the present study, using male C57BL/6 J mice, we explored whether resveratrol exerts ameliorative effects on cognitive impairment in adult offspring induced by prenatal exposure to inflammation and, if so, whether these effects were mediated through the activation of SIRT1." (PMID 38074521, 2023). "Moreover, a published study has reported that CAPE could reverse cadmium-induced cognitive impairment in mice through the AMPK/Sirt1 pathway." (PMID 36978961, 2023).
Cognitive impairment (continued). "Therefore, in the present study, we explored the effect of aerobic exercise on cognitive impairment in T2DM mice and investigated whether the JAK2/STAT3 and AMPK/SIRT1 pathways are involved in the underlying mechanism." (PMID 35578689, 2022). "Thus, activation of SIRT1 in the hippocampus through exercise may be beneficial against cognitive deficits, and could, at least in part, mediate some of the benefits of exercise observed in the present work." (PMID 33921628, 2021). "In this regard, we could not rule out the possibility that reactive oxygen species(ROS) released by BV2 activation contributed to neuronal SIRT1 inhibition, because increased ROS was generated in aged rodents of POCD models and associated with cognitive impairment." (PMID 33381265, 2020). "However, whether SIRT1 is involved in sevoflurane exposure-induced cognition impairment and whether resveratrol can provide neuroprotection against the neurotoxicity of sevoflurane still need to be further investigated." (PMID 32148659, 2020). "In our study, BML-111 up-regulated the level of SIRT1 and then suppressed the activation of NF-κB and deacetylation of NF-κB p65, which subsequently decreased the activation of microglia, reduced neuroinflammation, improved apoptosis cells and cognitive impairment." (PMID 30186119, 2018). "BML-111 could increase the level of SIRT1 and then inhibit the activation of NF-κB signaling pathway, which at last alleviated the activation of glias, mitigated neuroinflammation, decreased the number of apoptosis cells and improved cognitive impairment." (PMID 30186119, 2018). "To confirm the mediatory role of Sirt1 in the inhibitory role of H2S in CRS-induced cognitive deficits, we further explored whether Sirtinol (10nmol ×1w, i.c.v.), a specific Sirt1 inhibitor, reverses the protection of H2S against cognitive dysfunction in CRS-exposed rats." (PMID 29245987, 2017). "Therefore, we will explore whether the protection of H2S against CRS-induced cognitive impairment is also via upreglulating hippocampal Sirt1." (PMID 29245987, 2017). "SGB ameliorates cognitive impairment, neuroinflammation and neuronal apoptosis in white matter.SGB enhanced the expression of SIRT1 in the hippocampus and white matter, decreased NF-κB activity in the hippocampus and white matter." (PMID 40696697, 2025). "Our study suggests that EA‐induced activation of the SIRT1/FOXO1 autophagy signalling pathway and oxidative stress are involved in ameliorating postoperative cognitive impairment." (PMID 40008520, 2025). "Resveratrol, a specific SIRT1 activator, effectively counteracts the reduction in SIRT1 activity, ERK1/2 phosphorylation, tau hyperphosphorylation and cognitive impairment induced by lateral intraventricular injection of streptozotocin (ICV-STZ) in rats." (PMID 41228523, 2025). "Mammalian experimental studies have demonstrated that resveratrol activates both SIRT1 and AMPK signaling, which delays aging, extends lifespan, and improves cognitive deficits." (PMID 41228523, 2025). "According to a previous study, the activation of the SIRT1/PGC-1α pathway is beneficial to the protection of mitochondrial function, improving cognitive impairment and inhibiting neuroinflammation in rats with chronic cerebral hypoperfusion." (PMID 39796170, 2025). "The degree of cognitive deficits induced by CCH and the protective effect of baicalein and SIRT1 were assessed using the MWM test." (PMID 40290868, 2025). "Exercise has been shown to increase Sirt1 and BDNF levels, positively impacting aging-induced cognitive impairment and improving brain function." (PMID 41154548, 2025). "The role of sirtuin 1 (SIRT1) in neuroinflammatory initiation and cognitive deficits in aged rats after anesthesia and surgery." (PMID 39346790, 2024).
Cognitive impairment (continued). "In the current study, we found that the mRNA and protein levels of SIRT1 and PGC‐1α were decreased in the SD + saline group after CSD, implying that mitochondrial biogenesis dysfunction was involved in the cognitive impairment induced by CSD." (PMID 38688894, 2024). "The results demonstrated that during HIBI, ferroptosis occurs via the SIRT1/Nrf2/GPx4 signaling pathway, suggesting it as a potential therapeutic target for inhibiting ferroptosis and ameliorating HIBI‐induced cognitive impairments." (PMID 36184790, 2022). "Here, we report that BAI activated silent information regulator 1 (SIRT1) to deacetylate high-mobility group box 1 (HMGB1) protein in response to acute LPS-induced neuroinflammation and cognitive deficits." (PMID 33029280, 2020). "Furthermore, many researchers put their interests in the investigation between SIRT1 activator resveratrol and several animal models of brain injury, including subarachnoid hemorrhage, traumatic brain injury, middle cerebral artery occlusion, and cognitive impairment model." (PMID 33014276, 2020). "On the basis of these data, we proposed that EA upregulates SIRT1-PPARγ- PGC-1, which represses BACE1 expression, thereby reducing Aβ production and consequently improving cognitive deficits in an AD animal model." (PMID 26283960, 2015). "Additionally, SIRT1/VEGF is also critical to brain cognition, with evidence suggesting that inhibiting VEGF can lead to cognitive impairment." (PMID 40290868, 2025). "In general, overexpression of the NAMPT/SIRT1 mediated NAD + pathway in cancer and its subsequent suppression by chemotherapy may result in accelerated aging and cognitive deficits." (PMID 40085284, 2025). "NOR and FCT tests showed that Sirt1 overexpression ameliorated cognitive impairment in GBP-treated mice (GBP groups: eGFP vs. Sirt1, **p < 0.01, AAV-eGPF/saline and AAV-Sirt1/GBP: pre-context vs. pre-tone, *p < 0.05)." (PMID 40969938, 2025). "Overexpression of SIRT1/BDNF and specific activation of glutamatergic neurons in the hippocampal CA1 region have the potential to restore synaptic plasticity and improve postoperative cognitive impairment." (PMID 38783169, 2024). "Correlation analysis showed that plasma SIRT1 levels were associated with nonmotor symptoms such as depression, anxiety, EDS, and cognitive impairment and negatively correlated with quality of life in patients with PD." (PMID 37718350, 2024). "Plasma SIRT1 levels were negatively correlated with the age, Unified Parkinson’s Disease Rating Scale Part III (UPDRS-III) scores, anxiety, depression, excessive daytime sleepiness (EDS), quality of life, and especially cognitive impairment." (PMID 37718350, 2024). "The decline in SIRT1/BDNF levels leading to changes in synaptic plasticity and neuronal excitability in older mice could be a significant factor contributing to cognitive impairment after anesthesia/surgery." (PMID 38783169, 2024). "The administration of resveratrol after TBI significantly reduces the expression of P-p38 MAPK 86; increases the expression of SIRT1/PGC-1 signaling, including SIRT1, PGC-1, and synaptophysin (SYN); relieves edema; and increases the ability to fight cognitive impairment." (PMID 36906602, 2023). "A decrease in pro-inflammation cytokine concentrations and an increase in the expression levels of SIRT1, BDNF, PSD-95, and SYP in the hippocampus following resveratrol treatment contributed to reducing the cognitive deficits in offspring mice resulting from maternal immune activation." (PMID 38074521, 2023). "Thus, a possible explanation for our results is that the cognitive impairment manifested 4 months after the exposure to chronic stress, at the age of 6 months, may be related to accelerated senescence-related alternative splicing of Sirt1 in the cortex and TrkB in the hippocampus." (PMID 35563336, 2022).
Cognitive impairment (continued). "The activation of SIRT1 with resveratrol reverses the ICV-STZ-induced decrease in SIRT1 activity and the increase in ERK1/2 and tau phosphorylation, as well as the cognitive impairment in experimental animals, where SIRT1 protects hippocampal neurons from tau hyperphosphorylation." (PMID 30871086, 2019). "Although the link between SIRT1 and depressive symptoms in animal models has been demonstrated in the studies of Kishi and Chen, there is no research linking cognitive deficits and levels of SIRT1 on patients with schizophrenia." (PMID 31614739, 2019). "Via the AdipoR1/AMPK/SIRT1/SREBP2 signaling pathway, osmotin diminishes amyloidogenic Aβ production and aggregation, accompanied by improved pre- and post-synaptic dysfunction, cognitive impairment, memory deficits and long-term potentiation." (PMID 30871086, 2019). "Meanwhile, the involvement of resveratrol, an activator of SIRT1, in the protection of cognitive deficits is still not completely clear." (PMID 29164153, 2017). "In the ensuing paragraphs, we highlighted the involvement of SIRT1 in pathological processes of cognitive impairment in diabetic and nondiabetic models." (PMID 29164153, 2017). "Furthermore, Sirtinol, a Sirt1 inhibitor, reversed the protective effects of H2S against CRS-induced hippocampal damage and cognitive impairment." (PMID 29245987, 2017). "SIRT1 knockout mice or mutant mice lacking SIRT catalytic activity are associated with defects in synaptic plasticity in the hippocampus and induced cognitive deficits." (PMID 26732053, 2016). "Our previous studies demonstrated that EA at Dazhui (GV14) and Shenshu (BL23) in SAMP8 mice improves cognitive deficits, activates AMP-activated protein kinase (AMPK), and upregulates Sirtuin 1 (SIRT1)-dependent peroxisome proliferator- activated receptor-γ co-activator-1α (PGC-1α) expression." (PMID 26283960, 2015). "Furthermore, in T2D patients with cognitive impairment, increased expression of miR-34a-5p and decreased expression of sirtuin 1 (SIRT1) in peripheral blood was reported, as compared with T2D patients without cognitive impairment and healthy controls." (PMID 41277875, 2025). "Several studies using various animal models of depression and cognitive impairment have reported that resveratrol treatment alleviates cognitive deficits and reductions in BDNF and pCREB/CREB levels, likely through the modulation of neuroinflammation and the activation of the Sirt1/miR-134 pathway." (PMID 39684486, 2024). "Resveratrol holds promise as a novel treatment for cognitive impairment resulting from asymptomatic CASO, with its potential mechanisms primarily centered around the restoration of cerebral hemodynamic conditions, in which the NAD+/SIRT1/eNOS axis is presumed to play a pivotal role." (PMID 38716073, 2024). "This study demonstrated that reduced SIRT1/BDNF expression, impaired synaptic plasticity, and decreased neuronal excitability were observed in glutamatergic neurons in the CA1 region of mice after anesthesia/surgery, accompanied by significant cognitive impairment." (PMID 38783169, 2024). "Resveratrol pretreatment activated SIRT1 and mitigated neuroinflammation and cognitive impairment in POCD models in our previous study, but it remains unclear whether resveratrol would mitigate surgery and anesthesia-induced SIRT1 reduction and tau acetylation in aged POCD models." (PMID 33381265, 2020). "Furthermore, the modulating effect of TCA on BACE1 levels was associated with the upregulation of PPARγ, SIRT1, and PGC1α, negative regulators of BACE1 that ultimately led to the improvement in cognitive impairment without any effects in the WT mice." (PMID 32599846, 2020).